TNF (tumor necrosis factor)
Diseases named in the same sentence as TNF in open-access papers (continued):
Sharing a sentence is not in itself a finding about the gene and the disease.
COVID-19 (continued). "In this study, we identified an impaired type I IFN response in severe and critical COVID-19 patients, accompanied by high blood viral load and an excessive NF-κB–driven inflammatory response associated with increased TNF-α and IL-6." (PMID 32661059, 2020). "SARS-CoV-2 infection caused an overall downregulation of COVID-19 meta-interactome genes, with the exception of a small group of genes including TNF." (PMID 33456761, 2020). "The cytokine storm and profound inflammation seen in patients with severe COVID-19 are associated with macrophage and endothelial activation and surges in the levels of interleukin (IL)-1, IL-6, IL-8, and Tumor Necrosis Factor-alpha (TNF-α)." (PMID 33240937, 2020). "Recent evidence has implicated the development of cytokine release syndrome as the major cause of fatality in COVID-19 patients, with elevated levels of interleukin-6 (IL-6) and tumor necrosis factor alpha (TNF-α) observed in patients." (PMID 32587806, 2020). "For example, viral load in COVID-19 patients correlates highly with serum TNF-α levels, and severe COVID-19 disease is associated with high serum TNF-α." (PMID 33023255, 2020). "Lymphopenia and the levels of IL-6, IL-10, and TNF-α were found to be negatively associated with COVID-19 patient survival." (PMID 32967229, 2020). "Inflammatory cytokines IL1β, IL6, IL8, and TNFα associated with cytokine storm were significantly increased in the plasma of moderate and severe COVID-19 patients (p < 0.0001 for all cytokines)." (PMID 33585507, 2020). "For instance, both ascarid and hookworm infections appear to reduce IL-6 and TNF-α, elevated levels of which have been associated with increased COVID-19 severity." (PMID 33235797, 2020). "Macrophage produced TNF-α causes apoptosis of effector T cells, while IL-10 produced by lung macrophages in severe COVID-19 prevents T cell responses." (PMID 34192268, 2020). "Abnormal concentrations of several associated cytokines like TNF, IL-10, and IL-6 were found in COVID-19 patients." (PMID 33224256, 2020). "Moreover, in testicular autopsies of COVID-19 individuals, the intense expression of TNF-α was associated with reduced levels of BTB proteins, including Cx43." (PMID 41596343, 2026). "A caveat is that since our data are observational, we cannot determine whether elevated circulating TNF-α is a cause or a consequence of severe COVID-19." (PMID 40532694, 2025). "IL-6 and TNF are well-established mediators of acute inflammation, typically upregulated in response to viral infection and often associated with disease severity in COVID-19." (PMID 41007691, 2025). "Elevated cytokines IL-6, IFN-γ, and TNF-α have been associated with severe COVID-19 outcomes." (PMID 41035684, 2025). "The systemic inflammatory response associated with acute COVID-19, characterized by an exaggerated release of pro-inflammatory cytokines, such as IL-6 and TNFα, may disrupt protein turnover and muscle mass loss." (PMID 40283747, 2025). "In summary, IL-6 rs1800795 and TNF-α G-308 A, as common SNPs in both diseases, may explain the genetic factors underlying COVID-19-induced AIH at the genomic level." (PMID 39958350, 2025). "Rapid and sustained elevation of TNF-α is a hallmark of severe COVID-19." (PMID 41176818, 2025). "The underlying mechanisms may involve that IL-6 and TNF-α drive cytokine storms in severe COVID-19 and are elevated during active SLE phases, causing tissue damage in both lupus and viral infections." (PMID 40643149, 2025). "The COVID-19 pneumonia signal reflects temporal reporting patterns during the pandemic and suggests that TNF antagonists may be associated with a higher risk of severe COVID-19 in patients with IBD." (PMID 40763141, 2025). "Additionally, it was seen that of the many hallmarks inflammatory mediators analyzed, only IL-1, IL-6, and TNF had a significant association with post-acute sequelae of COVID-19 such as fatigue, dyspnea, and issues with concentration." (PMID 40333142, 2025).
COVID-19 (continued). "While haplotypes GGG and ACA were found for TLR8, with a dominance of haplotype ACA only in the TNFHIFNγN-L group, these results suggest that these genotypes may be associated with high TNF/IFN-γ levels during COVID-19." (PMID 39940907, 2025). "Lately, increasing studies point out that the "cytokine storm," characterized by the intense release of TNF-α and IL-6, could contribute to the mortality caused by COVID-19." (PMID 39854441, 2025). "Similarly, chronic inflammatory states are associated with excessive production of TNF-α, IL-6, and IL-1β, which occurs in severe forms of COVID-19, as well as in RA and chronic per-iodontitis." (PMID 41614780, 2025). "By lowering proinflammatory cytokines such as IL-6 and TNF-a, SGLT2is could mitigate the cytokine storm associated with severe COVID-19 cases." (PMID 40136608, 2025). "In our study, we described the demographical and clinical characteristics of patients with COVID-19 stratified by severity and assessed associations to infer the potential use of inflammatory cytokines (IL-2, IL-4, IL-6, IL-8, IL-10, TNF-α, GM-CSF, and IFN-γ) as biomarkers of COVID-19 pneumonia." (PMID 40508859, 2025). "Although immunosuppressed patients may have an increased risk of severe COVID-19 outcomes, anti-TNF therapy in IBD patients has been associated with a reduced risk of critical disease progression." (PMID 40573926, 2025). "For instance, in a retrospective study done in China involving 1,149 COVID-19 patients found that SUA levels over 6.7 mg/dL were associated with higher levels of the inflammatory markers such as tumor necrosis factor-α (TNF-a), Interleukin-6 (IL-6), and ferritin." (PMID 40333671, 2025). "Moreover, strong associations between the cytokines IFN-α/TNF-α and others observed in the COVID-19 group were lost in PLWH." (PMID 39861879, 2025). "The frequencies obtained from previous studies in the same population (Belem) showed that for the minor allele *A of the SNP rs1800629 (TNF -308G/A), the frequency ranged from 8.3% to 14.5%; given that the frequency for COVID-19 patients in our study was 9.9%, it fits in this range." (PMID 38675991, 2024). "Recently, an over-expression of TNF has been associated with taste dysfunction and, in particular, to taste distortion; E protein could, therefore, be the main cause of COVID-19 ageusia." (PMID 38928376, 2024). "The advancement of COVID-19 is driven by heightened oxidative phosphorylation, inflammatory responses associated with reactive oxygen species, and the displacement of inflammatory responses mediated by TNF and IL-6." (PMID 38337760, 2024). "Elevated levels of TNF have been linked to many diseases, including COVID-19." (PMID 38611791, 2024). "The complications, severity, and mortality of COVID-19 patients are caused by excessive activation of cytokines (IL-1, IL-6, TNF-a, CCL2, and CXCL10, etc.), namely cytokine storm, which is remarkably similar to the pathogenesis of immune disorders in RA patients." (PMID 38378889, 2024). "The risk of susceptibility to COVID-19 was significantly associated with TNF-α rs1800629 GA, GA+AA genotypes and the A allele, IL-8 rs4073 TA, AA genotypes and A allele, IL-10 rs1800872 GA and CC genotypes and C allele, and CXCR2 rs2230054 CT and CT+CC genotypes." (PMID 38544825, 2024). "TNF inhibition represents a promising immunomodulatory approach for COVID-19 treatment, given its potential to mitigate inflammation, particularly the pro-inflammatory cytokines associated with adverse outcomes in COVID-19 patients." (PMID 39459457, 2024). "Furthermore, autoimmune diseases can be triggered by COVID-19 in genetically predisposed patients, following the activation of an aberrant immune response by the cytokine cascade (TNF-α, IL-6, IL-1β, IL-17, and IL-18) induced by SARS-CoV-2." (PMID 38707102, 2024).
COVID-19 (continued). "Hence there is an urgent need for further research to understand the role of TNFα in CS, although recent research suggests that inhibition of the TNFα/NF-κB signaling pathway causes improvement in critically ill COVID-19 patients." (PMID 38694122, 2024). "The gene expression levels of cGAS, STING and the plasma levels of the cytokines IFN-α, TNF-α and IL-6 in patients with acute COVID-19 were evaluated according to factors considered risk factors for the severity of the disease, namely, sex, age and comorbidities." (PMID 38424312, 2024). "COVID-19 viral infection compared to infection caused by other viruses is characterized by increased pro-inflammatory cytokine levels such as IL-6, IL-1β, and TNF-α." (PMID 39063142, 2024). "Furthermore, COVID-19 patients had a higher frequency of the polymorphic A allele of TNF-α, the A allele of IL-8, the G allele of IL-10, and the T allele of CXCR2." (PMID 38544825, 2024). "Furthermore, increased levels of IFN-γ and TNF-α have been linked to the severity of COVID-19, reinforcing their potential role in disease progression." (PMID 38459174, 2024). "COVID-19 is also associated with immune activation that results in elevated levels of pro-inflammatory cytokines, including interleukin (IL): IL-2, IL-6, IL-7, and tumor necrosis factor-α (TNF-α)." (PMID 38881857, 2024). "Research shows that thyme and its bioactive compounds can suppress pro-inflammatory cytokines (e.g., TNF-α, and IL-6) and boost anti-inflammatory cytokines like IL-10, which may help manage inflammation linked to COVID-19." (PMID 39683135, 2024). "In COVID-19 patients, the level of inflammatory cytokines is increased and plays a crucial role in the pathogenesis of the disease; among them, interferon-γ (IFNγ), TNFα, IL-1β and IL-6 are indicated as the key cytokines associated with the severity of COVID-19." (PMID 38542436, 2024). "The cytokine triad of IL-1β, IL-6, and TNF is associated with the post-acute sequelae of COVID-19." (PMID 38932387, 2024). "Low-level heteroplasmy was significantly elevated in COVID-19 patients, especially in genes of the respiratory complex I. Both heteroplasmic variant burden and low-level heteroplasmy were associated with increased levels of IL-6, TNF-α, and IFN-α." (PMID 38377022, 2024). "However, cells from COVID-19 patients with the C allele significantly increase cytokine production when stimulated with spike + LPS, mainly IL-10, IL-6, and TNF-α compared to the unstimulated condition." (PMID 39456843, 2024). "Additionally, vitamin D suppresses the production of pro-inflammatory cytokines like interleukin-6 and tumor necrosis factor-alpha, potentially mitigating the cytokine storm associated with severe COVID-19 cases." (PMID 39564063, 2024). "Interestingly, in COVID-19 patients, markers of immune response such as TNF-α and IFN-γ were inversely associated with plasma ACBP levels." (PMID 39835130, 2024). "Moreover, the correlation and impact of miR-9 on the expression of pro-inflammatory cytokines IL-6, IL-1β, and TNFα, which are critical mediators in the inflammatory response associated with COVID-19 severity, were also assessed." (PMID 39201618, 2024). "This storm involves various immune cells, like B cells, T cells, and macrophages, all releasing high levels of pro-inflammatory cytokines such as interleukin-1 (IL-1), IL-6, and tumor necrosis factor-α (TNF-α), linked to the severe lung damage observed in many COVID-19 cases." (PMID 38732328, 2024). "Elevated levels of IL-6 and TNF-α are strongly associated with COVID-19 severity." (PMID 39408907, 2024). "In addition, their synergistic use in vivo also inhibited the elevation of pro-inflammatory cytokines, including IL-6 and TNF-α—the primary cytokines in the development of acute respiratory distress syndrome (the main cause of COVID-19 deaths)." (PMID 38383655, 2024).
COVID-19 (continued). "Thus, it is conceivable that the previously reported cytokine storm in severe COVID-19 predisposes for lung fibrosis, as we found the TNF-α pathway to be involved through TNFRSF12A." (PMID 39767799, 2024). "Pro-inflammatory cytokines such as IL-1, IL-10, IL-6, and TNF- α were found in significant concentrations in COVID-19 individuals, causing a cytokine storm during SARS-CoV-2 infection, which has been linked to ARDS, multi-organ failure, and increased candidate risk." (PMID 36608055, 2023). "The cytokine storm associated with severe COVID-19 is characterized by high levels of proinflammatory cytokines, including interleukin-1β (IL-1β), IL-2, IL-6, tumor necrosis factor (TNF), C-X-C motif chemokine ligand 10 or granulocyte-macrophage colony-stimulating factor (GM-CSF), among others." (PMID 37253946, 2023). "In a meta-analysis of 84 studies describing use of anti-TNF treatments it was concluded that TNF-α inhibitors are associated with a lower probability of hospitalization and severe COVID-19 when compared to any other treatment for an underlying inflammatory disease." (PMID 37064029, 2023). "However, elevated TNF-α levels have been linked with immunopathology in severe COVID-19 cases, while in TB, TNF-α is essential for granuloma formation and the containment of the infection." (PMID 38004820, 2023). "The breakdown of the BBB triggers a severe inflammatory response, causing the cytokine storm (release of IL-1β, IL-6, TNF-α, etc.)characteristic of the severe phase of COVID-19, which includes the recruitment of macrophages and lymphocytes and the activation of astrocytes and microglia." (PMID 36998270, 2023). "Hair loss in COVID-19 may be associated with the action of proinflammatory cytokines, such as interleukin 1β, interleukin 6, tumor necrosis factor α, and interferon-γ." (PMID 36674238, 2023). "Other studies have demonstrated that persistently elevated serum IL-6 levels during COVID-19 are independently associated with in-hospital mortality, and rises of serum IL-6, IL-8 and TNF-α are probably age-dependent, translating to poorer outcomes among the elderly." (PMID 37568402, 2023). "Inflammation is a key feature of COVID-19 and severe disease is associated with sudden release of pro-inflammatory cytokines such as IL-1, IL-6, TNF-α and interferon, called ‘cytokine storm’, leading to the migration of immune cells into the infection site, capillary damage, and multi-organ failure." (PMID 37817137, 2023). "In particular, PC1 reflected the known hyper-inflammatory phenotype of COVID-19 (with greatest contributions from IL-2, IL-6, IP-10, TNF-α, IL-10, IL-33 and IL-1β) which was independently associated with severe disease, requirement for invasive mechanical ventilation and mortality." (PMID 37063871, 2023). "Some biological disease-modifying anti-rheumatic drugs (DMARDs) such as TNF-α inhibitors may reduce the risk of COVID-19." (PMID 36987476, 2023). "It’s also suggested that Enterococcus may increase the production of pro-inflammatory cytokines such as TNF-alpha and IL-6, which have been shown to be elevated in patients with COVID-19 and are associated with severe disease." (PMID 36844398, 2023). "Of interest, numerous investigations have demonstrated that both moderate and severe COVID-19 instances may cause a hyperinflammatory reaction with increased levels of many cytokines such as IL-6, TNF-α, etc.." (PMID 37762499, 2023). "Furthermore, studies suggest that anti-TNF treatment is associated with a lower risk of COVID-19-related hospitalization and death." (PMID 37766088, 2023). "Acute COVID-19 was associated with marked elevations in nearly all pro-inflammatory markers, whilst eleven markers (namely IL-1β, IL-2, IL-6, IL-10, IL-18, IL-23, IL-33, TNF-α, IP-10, G-CSF and YKL-40) were associated with disease severity." (PMID 37063871, 2023).
COVID-19 (continued). "Severely ill COVID-19 patients display lung tissue damage associated with cell death and pathologic inflammation, which are linked to enhanced pro-inflammatory cytokine and chemokine levels (e.g., TNF-α and CXCL10)." (PMID 36992463, 2023). "Corticosteroids could affect COVID-19 severity, whereas anti-tumor necrosis factor α antibodies and thiopurines were associated with a reduced risk of severe COVID-19." (PMID 39131552, 2023). "A review study observed that variants in cytokine genes such as IL-1β, IL1R1, IL1RN, IL-6, IL-17A, FCGR2A, and TNF may be associated with disease susceptibility and/or severity, cytokine storm, and/or COVID-19 complications like thrombosis." (PMID 37662953, 2023). "We examined whether COVID-19-associated pEVs could modulate IL-1β/TNF-α/IL-8 expression in neutrophils." (PMID 37904132, 2023). "According to recent studies, the secretion of cytokines, such as interleukin (IL)-1β, IL6, and IL-10, and mediators such as TNF-α have been significantly stimulated in patients with COVID-19 and are associated with rapid disease progression in high-risk patients." (PMID 37047078, 2023). "TNF was significantly upregulated in patients and is commonly used to construct cellular inflammation models, making it a potential drug for simulating the inflammatory phenomena caused by COVID-19." (PMID 38050310, 2023). "In addition to the CD8+ T-cell defect, CD4+ T cells in COVID-19 cases also express the exhausted markers, and a high frequency of non-functional CD4+ T cells that are deficient at producing IFNγ, IL-2, and TNFα has been demonstrated in severe COVID-19 cases." (PMID 36839573, 2023). "TNF-α promoter polymorphism rs1800629 is associated with susceptibility and severity of COVID-19." (PMID 36833234, 2023). "In a recent study, it has been reported that depletion of gut microbiota in COVID-19 cohort was linked with increasing concentrations of TNF-α, CXCL10, CCL2 and IL-10 indicating that these taxa might have a role in reducing the ARDS associated cytokine storm." (PMID 37161621, 2023). "Furthermore, several inflammatory biomarkers of COVID-19, such as TNF-α, IL-6, ACE2, and NLR, were shown to be highly associated with ROS and RNS concentrations in patient sera." (PMID 37240319, 2023). "Several studies have observed associations between increasing TNF-α and the severity of COVID-19." (PMID 37109231, 2023). "In addition, TNF-α is also linked to bronchial hyperresponsiveness in COVID-19 patients, which causes them to suffer from decreased airway caliber and increased neutrophilia in respiratory epithelia." (PMID 37047115, 2023). "Importantly, increased levels of TNF-α and IL-6 are associated with the severity of disease in COVID-19 patients." (PMID 36864506, 2023). "Notably, heightened TNFα levels have been correlated with a higher risk of mortality in COVID-19 cases and were associated with cellular injury." (PMID 36960064, 2023). "Interestingly, we found that IL-10, IL-23, and TNF-α were strongly associated with COVID-19 mortality, as demonstrated by ROC curve and multivariate regression analysis." (PMID 37283736, 2023). "CBD was also shown to reduce interleukin (IL)-2, IL-1α and β, interferon gamma, inducible protein-10, monocyte chemoattractant protein-1, macrophage inflammatory protein-1α, and tumor necrosis factor-α – all of which are associated with the pathology of severe cases of COVID-19." (PMID 36844029, 2023). "Furthermore, IL-1, IL-6 and TNF-α produced by macrophages have been reported as pathogenic factors in the excessive inflammatory response in COVID-19." (PMID 37969879, 2023). "However, the brain inflammation associated with COVID-19 increases the concentration of cytokines that negatively affect adult human neurogenesis, e.g., IL-6, IL-1β, IL-1α, and TNF." (PMID 36672177, 2023).